PAX8 (paired box 8)
Diseases named in the same sentence as PAX8 in open-access papers (continued):
Sharing a sentence is not in itself a finding about the gene and the disease.
sarcoma (5 papers, 2017 to 2025). A usually aggressive malignant neoplasm of the soft tissue or bone. "In this case report, PAX8 was a diagnostic clue for revising a previous diagnosis of unclassified high grade sarcoma to diffuse large B-cell lymphoma." (PMID 28634564, 2017). "Most uRCCs are at least focally positive for these markers; if PAX8 is absent, metastatic carcinoma or sarcoma should be reconsidered." (PMID 41426798, 2025). "The combined demonstration of PAX8 and cytokeratin positivity essentially confirms sarcomatoid carcinoma rather than a primary sarcoma." (PMID 41426798, 2025). "Furthermore, WTs are PAX8 positive, while neuroblastoma, DSRCT and sarcoma are PAX8 negative." (PMID 32204536, 2020).
adenoma (4 papers, 2019 to 2023). A neoplasm arising from the epithelium. "The two mutation-positive ≥4-cm adenomas had fusion PAX8/PPARG and mutant HRAS." (PMID 31780751, 2019). "The expression levels of Pax8, Cdh1 and Muc16 trended to be higher in both the sex cords and adenoma samples, as compared to the naïve and mature GC controls." (PMID 37174061, 2023). "The expression of Pax8 was significantly higher in sex cords versus mature GCs (p = 0.029), and Cdh1 (p = 0.017) expression was significantly higher in the adenoma compared to all other phenotype groups." (PMID 37174061, 2023). "PAX8/GLIS3 was identified in the one hyalinizing trabecular adenoma, consistent with a recent report." (PMID 31572297, 2019).
athyreosis (4 papers, 2013 to 2025). Athyreosis is a form of thyroid dysgenesis characterized by complete absence of thyroid tissue that results in primary congenital hypothyroidism, a permanent thyroid deficiency that is present from birth. "TD represents approximately 80–85% of CH cases and includes conditions such as ectopy, athyreosis, and orthopic hypoplasia, which are rarely linked to mutations in transcription factor genes like TSHR, PAX8, and NKX2-1." (PMID 40981308, 2025).
cholangiocarcinoma (4 papers, 2016 to 2025). A carcinoma that arises from the intrahepatic biliary tree (intrahepatic cholangiocarcinoma) or from the junction, or adjacent to the junction, of the right and left hepatic ducts (hilar cholangiocarcinoma). "These metastases were positive for PAX8, that is a well-established marker for primary and metastatic RCC and CDH16, which is a specific renal protein, while they were negative for the bile ducts and cholangiocarcinoma marker CK7 (Cytokeratin 7), consistent with their renal origin." (PMID 27668431, 2016).
Insulin resistance (4 papers, 2019 to 2025). Increased resistance towards insulin, that is, diminished effectiveness of insulin in reducing blood glucose levels. "Pax8 +/- mice exhibited an increased homeostatic assessment of insulin resistance (HOMA-IR) index, which was caused by fasting hyperinsulinemia." (PMID 31518338, 2019). "Pax8 +/- mice displayed severe insulin resistance, as determined by increased AUC during the insulin tolerance test (ITT)." (PMID 31518338, 2019). "Confirming the insulin resistance observed in metabolic tests, western blots performed in liver extracts revealed a decrease in pSer473 Akt in Pax8 +/- mice." (PMID 31518338, 2019). "Mild hypothyroid Pax8 +/- mice were heavier and displayed insulin resistance, hepatic steatosis and increased prevalence of liver cancer yet had normal lifespan." (PMID 31518338, 2019). "Nevertheless, male Pax8+/− mice (8 and 24 months-old animals) with age exhibit a mild but significant decrease in circulating T4 levels correlating with mild glucose intolerance and increased insulin resistance, a phenotype resembling T2DM." (PMID 31817798, 2019). "These genes have been involved in insulin resistance and secretion (ATM, PTPRN2, PSMD10, and NSF), adipogenesis (SLC25A24 and PAX8), inflammatory processes (TNFRSF8 and SLIT3), and mitochondrial processes (PM20D1 and LCLAT1)." (PMID 36535927, 2022).
pancreatic NETs (4 papers, 2013 to 2024). "CDX2 shows high sensitivity and specificity for small intestinal NENs, whereas PAX8 is used to identify primary and metastatic pancreatic NETs." (PMID 32245475, 2020). "Furthermore, PAX8 has been recognized as a potential immunohistochemical marker of pancreatic neuroendocrine tumors." (PMID 23425942, 2013). "Among liver metastases, only pancreatic neuroendocrine tumors (20/31, 65%) were PAX8-positive, whereas no cases of ileal, pulmonary, duodenal and rectal neuroendocrine tumor metastases were PAX8-positive." (PMID 23425942, 2013). "Many laboratories have switched from polyclonal to better-performing (for adenocarcinoma applications) monoclonal PAX8 antibodies, the latter of which are non-reactive in pancreatic NETs (i.e., polyclonal PAX8-positivity in pNETs is due to cross-reactivity with PAX6)." (PMID 39062773, 2024).
Renal cyst (4 papers, 2021 to 2026). A fluid filled sac in the kidney. "A renal-specific, DOX-inducible Pkd1 KO model (Pkd1fl/fl:Pax8-rTTA:TetO-Cre) was next used to determine if Tfeb was similarly affected in renal cysts that arise due to Pkd1 deletion." (PMID 36794754, 2023). "Thus, nuclear translocation of Tfeb appears to be both an early and a sustained event in the development of renal cysts in both Flcnfl/fl:Ksp-Cre and Pkd1fl/fl:Pax8-rTTA:TetO-Cre models." (PMID 36794754, 2023). "When SCH23390 was administered chronically, renal cyst formation was slowed only in Pkd2fl/fl;Pax8-rtTA;Tet-O-Cre mice but not in Pkd1fl/fl;Pax8-rtTA;Tet-O-Cre mice." (PMID 33886508, 2021). "Importantly, Pax8 lineage recombination in these mice occurs in tubular epithelium, but not in vasculature, providing a model of cystic kidney disease in which Pkd1 is not deleted from ECs." (PMID 40114603, 2025).
angiomyolipoma (3 papers, 2022 to 2025). A neoplasm with perivascular epithelioid cell differentiation often associated with tuberous sclerosis. "However, cases of ESC-RCC with epithelioid angiomyolipoma characteristics have been reported, and the tumor cells express Melan-A, melanosome-associated antigen, CK20, and PAX8, among which CK20 and PAX8 may be effective for a differential diagnosis." (PMID 37098579, 2023). "ESC RCC can express Melan A, HMB45 or Cathepsin K. PAX-8 positivity rules out an epithelioid angiomyolipoma, in addition to absence of other morphological features of AML." (PMID 34514562, 2022).
B-cell lymphomas (3 papers, 2017 to 2022). "Additionally, B-cell lymphomas stain positive on polyclonal PAX8 preparation, while also manifesting cross-reaction with PAX5." (PMID 36428491, 2022).
bladder cancer (3 papers, 2022 to 2024). "The significant association between high PAX8 expression and low tumor grade in non-invasive (pTa) urinary bladder cancers fits well to the weak to moderate nuclear PAX8 staining that was occasionally seen in normal urothelium, which appears to be lost during tumor progression." (PMID 39105782, 2024). "The discovery in the present study that JorA increases Bid expression and decreases Bcl2, Bcl-XL, and Pax8 expression suggests that JorA accelerates the apoptosis of bladder cancer cells from multiple angles." (PMID 37587470, 2023). "In conclusion, this study revealed that the expression of hsa_circ_0139402 is more highly in BC tissues and cell lines, and hsa_circ_0139402 promotes bladder cancer progression by regulating hsa-miR-326/PAX8 signaling." (PMID 35154515, 2022). "This study also investigated whether or not hsa_circ_0139402 promotes bladder cancer cell proliferation, migration, and invasion by regulating hsa-miR-326/PAX8 signaling." (PMID 35154515, 2022).
carcinoid (3 papers, 2023 to 2025). "The interface between struma ovarii and carcinoid showed strong PAX-8 and uniform TTF-1 staining in the struma but gradual loss of TTF-1." (PMID 40428242, 2025). "Retained/weak PAX-8 staining was noted, moving away from the struma component and into the carcinoid." (PMID 40428242, 2025). "This is reflected in other literature, where the protective effect of carcinoid tumors as inert tumors in PNETs may be due to the differential expression of the transcription factor PAX8.27." (PMID 37296397, 2023). "In contrast, the carcinoid was focally interspersed positive for TTF-1, patchy positive for CDX-2 and PAX-8, and CD56 (basal and cytoplasmic), strongly positive for synaptophysin, and negative for GATA-3, calretinin, and chromogranin-A." (PMID 40428242, 2025). "IHC analysis revealed a similar immunophenotype of ovarian strumal carcinoid with normal thyroid tissue, wherein the strong positive reaction of thyroid-specific transcription factor-1 (TTF-1) and PAX8 was a significant feature." (PMID 41244794, 2025).
Coma (3 papers, 2019 to 2022). The complete absence of wakefulness and consciousness, which is evident through a lack of response to any form of external stimuli. "Another paper described a single nucleotide polymorphism (SNP) in the PAX8 locus in Afro-Americans that correlated with elevated risk of type II diabetes." (PMID 35806410, 2022). "The father had suffered from type 2 diabetes, while the daughter developed gestational diabetes mellitus, further implicating PAX8 in pancreatic islet cell function during pregnancy." (PMID 35806410, 2022).
Infertility (3 papers, 2021 to 2024). "In an experimental study, Pax8-deficient female mice were reported with infertility independently of thyroid replacement therapy, and a possible role in MD development was suggested." (PMID 38699388, 2024). "In mice, PAX8 knockouts demonstrate male and female infertility and multiple genitourinary and reproductive anomalies." (PMID 39639036, 2024). "Importantly, the thyroid defects of PAX8 KO mice can be rescued by administration of levothyroxine revealing an infertility phenotype due to defects in the urogenital tract." (PMID 33903593, 2021).
liver cancer (3 papers, 2018 to 2020). An epithelial or non-epithelial malignant neoplasm that arises from the liver. "Taken together these data suggest that severe loss of TH in Pax8-/- mice is lethal while modest reduction observed in Pax8 +/- mice is associated with altered metabolism as assessed by increased susceptibility to obesity and liver cancer." (PMID 31518338, 2019). "Data generated in the murine model of PAX8 deficiency suggest that humans bearing PAX8 mutations might have greater propensity to develop metabolic complications and liver cancer." (PMID 33048427, 2020). "Mild hypothyroid PAX8 heterozygous knockout mice exhibit an ~threefold increase in the prevalence of liver cancers." (PMID 33048427, 2020).
mucinous cystadenoma (3 papers, 2019 to 2026). A benign or low malignant potential cystic epithelial neoplasm composed of cells which contain intracytoplasmic mucin. "These cells and their derived tumors show positive expression for the CK7, PAX8, and MUC1 proteins, confirming that they are of epithelial origin, possibly from mucinous adenoma or borderline lesion." (PMID 40427213, 2025). "Two of the mucinous cystadenomas were associated with teratoma; both were consistently negative for CK20, CDX2, and PAX8." (PMID 31771640, 2019).
mucinous ovarian tumors (3 papers, 2019 to 2022). "PAX8 is a sensitive and specific marker for tumors of Müllerian origin but it is less commonly expressed in ovarian mucinous tumors, with a range therein from 0% to 70%." (PMID 31771640, 2019). "It is conceivable that benign MLPs may have ability to differentiate to lineage-specific mucinous lesions, and, as such, they may serve as a possible new origin of some ovarian mucinous neoplasms; in particular, Pax8-positive tumors." (PMID 36010251, 2022). "Although 30% of mucinous ovarian tumors (n = 104) had IHC performed for CK7, CK20, CDX2, SATB2, and PAX8 in a prior study, we were unable to perform this diagnostic panel on all cases and could not confirm whether they were done as part of routine pathologic assessment." (PMID 36222710, 2022).
neuroendocrine carcinoma (3 papers, 2013 to 2025). A malignant neuroendocrine neoplasm composed of cells containing secretory granules that stain positive for NSE and chromogranin. "The lack of synaptophysin expression effectively excludes a neuroendocrine carcinoma, along with the absence of PAX8, which renders primary carcinomas of the thyroid, kidney, or ovaries unlikely." (PMID 41584573, 2025). "In addition, the expression of PAX8 (clone SP348), WT1, Napsin A, or TTF1 (clone 8G7G3/1) is never or almost never present in TNBC (the latter outside of the context of neuroendocrine carcinoma)." (PMID 37306115, 2024).
non-small cell lung carcinoma (3 papers, 2014 to 2018). A group of at least three distinct histological types of lung cancer, including non-small cell squamous cell carcinoma, adenocarcinoma, and large cell carcinoma. "PAX8 is reported to be expressed in metastatic non-small cell lung cancers and to promote cell migration via interaction with MET and RON." (PMID 29535844, 2018). "It was previously reported that PAX8 and PAX5 are highly expressed in non-small cell lung cancer (NSCLC) and small cell lung cancer cell lines, respectively; but little is known regarding PAX6 expression and function in lung cancer." (PMID 24454925, 2014).
ovarian endometrioid carcinoma (3 papers, 2025). "The same authors also showed that TOV-112D cells, a line reported to originate from ovarian endometrioid carcinoma, express neither CK7, PAX8 nor ER." (PMID 39878900, 2025).
peritoneal mesothelioma (3 papers, 2013 to 2024). A benign or malignant mesothelial neoplasm that arises from the peritoneum. "Through a literature search, Chapel and Husain reported 27 cases of peritoneal mesothelioma, of which five cases were positive for PAX-8, including three female patients with diffuse (>50% of the tumor nuclei) staining and two male patients with focal (<50% of the tumor nuclei) staining." (PMID 39605894, 2024). "Interestingly, PAX8 expression is observed in peritoneal mesotheliomas, but not in pleural mesotheliomas." (PMID 29701689, 2018).
salivary gland tumors (3 papers, 2021 to 2024). "While some of these markers can be found in salivary gland tumors, PAX-2, PAX-8, and hKIM-1 typically show negative reactivity in such tumors." (PMID 39931206, 2024).
serous cystadenoma (3 papers, 2021 to 2022). A serous neoplasm in which the cysts and papillae are lined by a single layer of cells without atypia, architectural complexity or invasion. "Previously, PAX8 expression was detected in 77% (23/30) of serous cystadenomas using immunohistochemistry." (PMID 35326657, 2022). "In such cases, careful microscopic evaluation along with IHC staining can differentiate the two tumors as serous cystadenoma cells do not express CD10 and PAX-8 and RCC but are positive for CK7 while RCC cells are negative for CK7 and positive for CD10 and PAX-8." (PMID 34034720, 2021).
serous uterine carcinoma (3 papers, 2015 to 2022). "We have shown that in uterine serous papillary carcinoma, PAX8 plays a pro-proliferative and anti-apoptotic role that is mediated via transcriptional activation of cytoplasmic p21, which has an anti-apoptotic role in this disease." (PMID 35806410, 2022).
upper tract urothelial carcinoma (3 papers, 2016 to 2026). "However, additional histopathological and immunohistochemical examinations (i.e., GATA3, P63, PAX8) may be required for diagnosis as it is sometimes difficult to differentiate CDC from upper tract urothelial carcinoma (UTUC) that originates from the same anatomical region." (PMID 27484008, 2016). "The observed weak PAX8 expression was of limited utility, as weak expression may be seen in upper tract urothelial carcinomas and may show attenuated to negative expression in a sarcomatoid renal cell carcinoma." (PMID 40691018, 2025). "Nivolumab + cabozantinib reduced the lesion before nephrectomy, which showed predominantly pleomorphic tumor cells that were PAX8 negative and GATA3/p63 positive, mimicking upper tract urothelial carcinoma." (PMID 42317258, 2026).
uterine corpus endometrial carcinoma (3 papers, 2019 to 2022). A endometrial carcinoma (disease) that involves the body of uterus. "We observed similar features in the uterine corpus endometrial carcinoma dataset: the genes with the highest frequency included SOX17 and C3 (8%), PAX8, MME and ESR1 (7%)." (PMID 31879572, 2019).
acute lymphoblastic leukemia (2 papers, 2021 to 2023). Leukemia with an acute onset, characterized by the presence of lymphoblasts in the bone marrow and the peripheral blood. "For instance, increasing the expression of SMN2 may have clinical utility in patients with spinal muscle atrophy owing to SMN1 mutations, and increased expression of PAX2 or PAX8 may be of interest in patients with predisposition to acute lymphoblastic leukemia due to PAX5 mutations." (PMID 34818036, 2021).
breast tumors (2 papers, 2019 to 2020). "Conversely, Paired-box gene 8 (PAX8) in most cases of ovarian cancer is frequently expressed, while in breast tumors is negative." (PMID 31344859, 2019).
cervical tumor (2 papers, 2021 to 2024). "PAX8 positivity favors a primary cervical tumor diagnosis, but not all gastric-type endocervical adenocarcinomas of the cervix are PAX8-positive." (PMID 33570865, 2021). "Typically, ER and PR are not expressed, while PAX8 may be positive in these cervical tumors." (PMID 39040449, 2024).
endocervical adenocarcinoma (2 papers, 2020 to 2021). An adenocarcinoma that arises from the endocervix. "PAX-8 was positively expressed in 9 endometrial adenocarcinoma, 1 endocervical adenocarcinoma and 1 ovarian mucinous cyst adenocarcinoma, 2 poorly, and 1 moderately differentiated SCC." (PMID 32847623, 2020).
epithelial ovarian tumors (2 papers, 2012 to 2019). "PAX-8 is known to be expressed in a variety of ovarian epithelial tumors." (PMID 23044077, 2012). "MC is likely to be negative for PAX8 as it is believed that MC originates from a tissue other than the Müllerian duct CK7 and E-cadherin are commonly seen in epithelial ovarian tumors." (PMID 31248002, 2019).
epithelioid mesothelioma (2 papers, 2017 to 2023). "It should be noted that most epithelioid mesotheliomas express GATA3, and some may also be positive for PAX8." (PMID 37461124, 2023).
Ewing sarcoma (2 papers, 2016 to 2020). A small round cell tumor that lacks morphologic, immunohistochemical, and electron microscopic evidence of neuroectodermal differentiation. "Poor prognostic features were found in two other patients: low expression of PAX8, FHIT, CASP10, CHD2, with high expression of CHD11, FUS, and MTA1 in a patient with Ewing sarcoma, and gain of 1q and loss of 6q and overexpression of TNC, CALB1, PLAG1, ALDH1L1, and RELN in a patient with ependymoma." (PMID 28007021, 2016).
gestational diabetes (2 papers, 2019). Carbohydrate intolerance first diagnosed during pregnancy. "We also previously demonstrated that TH delayed beta cell loss under stress conditions and that mutations on PAX8 are found in patients developing gestational diabetes." (PMID 31518338, 2019). "More recently, PAX8, for which SNPs are also associated with T2DM in GWAS, was identified as the first gestational diabetes mellitus (GDM) candidate gene critical for islet survival during pregnancy." (PMID 31072002, 2019).